PTGDS (prostaglandin D2 synthase)
Description:
Catalyzes the conversion of PGH2 to PGD2, a prostaglandin involved in smooth muscle contraction/relaxation and a potent inhibitor of platelet aggregation. Involved in a variety of CNS functions, such as sedation, NREM sleep and PGE2-induced allodynia, and may have an anti-apoptotic role in oligodendrocytes. Binds small non-substrate lipophilic molecules, including biliverdin, bilirubin, retinal, retinoic acid and thyroid hormone, and may act as a scavenger for harmful hydrophobic molecules and as a secretory retinoid and thyroid hormone transporter. Possibly involved in development and maintenance of the blood-brain, blood-retina, blood-aqueous humor and blood-testis barrier. It is likely to play important roles in both maturation and maintenance of the central nervous system and male reproductive system. Involved in PLA2G3-dependent maturation of mast cells. PLA2G3 is secreted by immature mast cells and acts on nearby fibroblasts upstream to PTDGS to synthesize PGD2, which in turn promotes mast cell maturation and degranulation via PTGDR (By similarity).
Synonyms: L-PGDS; PGDS; PGDS2; PDS; LPGDS; PGD2
Tractability: Small molecule: an approved drug acts on it; a structure with a bound ligand is known; it has a high-quality binding pocket. Antibody: UniProt places it where antibodies can reach, with high confidence; its Gene Ontology location is reachable by antibodies, with high confidence; UniProt predicts a signal peptide or a membrane-spanning region.
Target class: Isomerase; Enzyme
Gene: Protein-coding gene on chromosome 9 (136,975,053 to 136,981,750, forward strand). Ensembl gene ENSG00000107317.
Subcellular location: Rough endoplasmic reticulum; Nucleus membrane; Golgi apparatus; Cytoplasm, perinuclear region; Secreted
Pathways (Reactome):
Developmental Biology: Transcriptional regulation of testis differentiation
Metabolism: Synthesis of Prostaglandins (PG) and Thromboxanes (TX)
Gene Ontology:
Molecular function: fatty acid binding; prostaglandin-D synthase activity; protein binding; retinoid binding; lipid binding; small molecule binding
Biological process: prostaglandin biosynthetic process; prostanoid biosynthetic process; regulation of circadian sleep/wake cycle, sleep; cyclooxygenase pathway; gene expression; response to glucocorticoid
Cellular component: extracellular exosome; extracellular region; rough endoplasmic reticulum; endoplasmic reticulum membrane; Golgi apparatus; nuclear membrane; perinuclear region of cytoplasm
Genetic constraint (gnomAD): Loss-of-function variants: 21 observed, 28.8 expected, observed/expected ratio (o/e) 0.73, 90% interval 0.52 to 1.05. The upper end of that interval is the gene's LOEUF score, 1.05, which puts it in group 4 of 6, group 1 being the genes least tolerant of losing a copy. Missense variants: 236 observed, 248.13 expected, observed/expected ratio (o/e) 0.95, 90% interval 0.85 to 1.06. Synonymous variants: 101 observed, 109.28 expected, observed/expected ratio (o/e) 0.92, 90% interval 0.79 to 1.09.
Homologues: Orthologues: chimpanzee PTGDS (99% identical), macaque PTGDS (94% identical), guinea pig PTGDS (73% identical), dog PTGDS (72% identical), mouse Ptgds (72% identical), rat Ptgds (69% identical), tropical clawed frog obp (35% identical), zebrafish ptgdsb.1 (29% identical), zebrafish ptgdsb.2 (27% identical), zebrafish zgc:153704 (26% identical). Paralogues in human: LCN2 (31% identical), LCN15 (29% identical), LCN12 (25% identical), OBP2B (20% identical), OBP2A (19% identical), LCN6 (19% identical), LCN10 (18% identical), LCN1 (16% identical), LCN9 (16% identical), PAEP (16% identical), LCN8 (15% identical), LCNL1 (14% identical).
Diseases named in the same sentence as PTGDS in open-access papers:
PTGDS is named in the same sentence as 157 diseases in open-access papers, as found by Europe PMC text mining. Sharing a sentence is not in itself a finding about the gene and the disease. The quoted sentences say what the papers report.
meningioma (14 papers, 2008 to 2025). A generally slow growing tumor attached to the dura mater. "Both also expressed PTGDS, and thus cannot be distinguished based on findings in mice, where meningioma can be generated by expression of NF2 in PTGDS-expressing primordial meningeal cells." (PMID 40672210, 2025). "Second-generation GEMMs used for meningioma research introduced modifications to promoter of the prostaglandin-D2-synthase (PGDS) gene to establish meningiomas in mice." (PMID 38001599, 2023). "Our study validated the higher expression of PTGDS in Grade I meningioma as compared to Grade II, however the expression of this protein was found to be upregulated in GBM in comparison to LGG." (PMID 34055594, 2021). "Shortly after these initial studies, prostaglandin D2 synthase (PTGDS) was identified as a specific marker for meningioma precursor cells." (PMID 31652973, 2019). "Studies in genetically engineered mice suggest that meningiomas arise from prostaglandin D2 synthase (PGDS) expressing arachnoid cells which protrude through the dura on arachnoid villi." (PMID 31970090, 2019). "Additionally, prostaglandin H2 D-isomerase (PTGDS) has been proposed as a potential biomarker of meningiomas." (PMID 38001599, 2023). "This sheds light on CSF prostaglandin D2 synthase that could be tested as a potential biomarker of meningiomas." (PMID 38001599, 2023). "The protein PTGDS has been reported as a potential biomarker of meningioma in multiple studies." (PMID 34055594, 2021). "Three peptides of 5 Proteins which includes APOA1, APOE, PTGDS, VTN and C3 were monitored for both Meningioma and Glioma samples." (PMID 34055594, 2021). "For the meningioma CSF samples, three peptides of APOE (SELEEQLTPVAEETR, LGPLVEQGR and AATVGSLAGQPLQER) gave a cumulative fold change of 2.21 whereas peptides of PTGDS (WFSAGLASNSSWLR, TMLLQPAGSLGSYSYR and AQGFTEDTIVFLPQTDK) showed a fold change of 1.52." (PMID 34055594, 2021). "Kim et.al., reported that expression of PTGDS using Western blot was found to be decreased in Meningioma CSF when compared to non-tumor controls." (PMID 34055594, 2021).
atherosclerosis (10 papers, 2008 to 2023). A disease characterized by the build-up of fatty material and calcium deposition in the arterial wall resulting in partial or complete occlusion of the arterial lumen. "Expression of PTGDS can be induced in vascular endothelial cells by laminar fluid shear stress and thus is associated with progression of atherosclerosis." (PMID 28407751, 2017). "The expression of the genes ADORA1, involved in myocardial ischemia and dilated cardiomyopathy, and PTGDS, recently associated with the progression of atherosclerosis were significantly up-regulated in EAT." (PMID 21603615, 2011). "Levels of the prostaglandin D2 synthase (PTGDS) gene, recently associated with the progression of atherosclerosis, were significantly different in the three pairwise comparisons (EAT>MAT>SAT)." (PMID 21603615, 2011). "PTGDS knockout mice developed atherosclerosis when compared with controls." (PMID 21603615, 2011). "Furthermore, impaired PTGDS expression could lead to the accumulation of lymphocytes and macrophages, accelerating the development of atherosclerosis." (PMID 37762221, 2023). "The fact that PTGDS and SASH1 expression remained associated with carotid plaques after adjustment on smoking status may indicate a broader implication of these genes in atherosclerosis than the sole effect induced by smoking." (PMID 20502693, 2010). "Furthermore, PTGDS and DGKE may have crucial roles in the progression of CAD atherosclerosis." (PMID 36088434, 2022).
gastric cancer (10 papers, 2019 to 2025). A primary or metastatic malignant neoplasm involving the stomach. "Several other studies have reported that PTGDS expression is lower in gastric cancer tissues compared with PTGDS, which was associated with better prognosis." (PMID 30393234, 2019). "As the key metabolic enzyme in PGD2 production, PTGDS knockdown reduced the level of PGD2 in gastric cancer stem cells, and promoted the viability, invasion, and stemness of tumor cells through binding to PGD2 receptor." (PMID 39706989, 2025). "Other researchers, however, discovered that PTGDS was downregulated and prevented tumor growth in gastric cancer, cervical squamous cell carcinoma, lung tumors, and prostate tumors." (PMID 39641239, 2024). "In our previous study, lipocalin-type prostaglandin D2 synthase (L-PGDS) showed inhibitory effects on gastric cancer growth." (PMID 35087591, 2022). "Whereas, other studies identified that PTGDS was downregulated in prostate tumors, non-small cell lung cancer, and gastric cancer." (PMID 34743203, 2022). "In contrast, other researchers found that PTGDS was down-regulated and inhibited tumor progression in prostate tumors, lung tumors, and gastric cancer." (PMID 34743203, 2022). "PTGDS have been shown to be selectively expressed in cancers, including ovarian cancer and melanoma with overexpression, gastric cancer and lung cancer with low expression." (PMID 36733384, 2022). "As the main synthetase of PGD2, PTGDS had also been shown to be downregulated in multiple tumours, such as lung cancer 38, gastric cancer 39, prostate cancer 40, and cervical cancer." (PMID 32047563, 2020). "Prostaglandin D2 (PGD2) synthase (PTGDS) and its receptor PTGDR2 are negatively correlated with stem genes (Sall4 and Lgr5) in gastric cancer, which restricts tumor self-renewal, growth, and metastasis by relying on the PTGDR2 pathway to inhibit STAT3 phosphorylation and nuclear expression." (PMID 33312950, 2020).
Alzheimer disease (8 papers, 2013 to 2025). A progressive, neurodegenerative disease characterized by loss of function and death of nerve cells in several areas of the brain leading to loss of cognitive function such as memory and language. "In patients with Alzheimer's disease, PTGDS is primarily expressed in oligodendrocytes." (PMID 40974022, 2025).
prostate carcinoma (7 papers, 2008 to 2024). A carcinoma that arises from epithelial cells of the prostate gland. "We found that a synergistic gene pair that includes PTGDS obeys the same "molecular logic" as RBP1, i.e. prostate cancer occurs in the simultaneous low expression of PTGDS and high expression of the partner gene." (PMID 18234101, 2008). "PTGDS was downexpressed and has the potential to predict biochemical relapse in prostate cancer." (PMID 35075375, 2022). "The most interesting 8 prognostic biomarkers for prostate cancer included lncRNA LINC01082, miRNA hsa-miR-133a-3p, and genes TTLL12, PTGDS, GAS6, CYP27A1, PKP3, and ZG16B." (PMID 35075375, 2022). "lncRNA LINC01082, miRNA hsa-miR-133a-3p, and genes TTLL12, PTGDS, GAS6, CYP27A1, PKP3, and ZG16B are the top RNAs having the potential to predict prognosis for prostate cancer." (PMID 35075375, 2022). "We constructed ceRNA networks in the prostate cancer microenvironment and identified lncRNA LINC01082, miRNA hsa-miR-133a-3p, and genes TTLL12, PTGDS, GAS6, CYP27A1, PKP3, and ZG16B as the potential biomarkers to predict prognosis for prostate cancer." (PMID 35075375, 2022). "Finally, survival analysis, biological function analysis, and literature researched identified 8 key biomarkers (lncRNA LINC01082, miRNA hsa-miR-133a-3p, mRNA TTLL12, PTGDS, GAS6, CYP27A1, PKP3, and ZG16B) to predict prostate cancer prognosis." (PMID 35075375, 2022).
Hypertension (6 papers, 2008 to 2025). The presence of chronic increased pressure in the systemic arterial system. "PTGDS is upregulated in early diabetes and is a marker of hypertension and latent renal injury." (PMID 22091387, 2011). "The differential up-regulation of PTGDS and ADORA1 suggests a possible cardioprotective role of EAT toward CAD, hypertension, and other cardiovascular dysfunctions." (PMID 21603615, 2011).
multiple sclerosis (6 papers, 2008 to 2024). A progressive autoimmune disorder affecting the central nervous system resulting in demyelination. "An increased PTGDS expression has been reported in multiple sclerosis lesions and in human and animal models of demyelination where it seems to be restricted to oligodendrocyte-lineage cells and reactive astrocytes in the lesioned white matter." (PMID 25966014, 2015).
Azoospermia (5 papers, 2020 to 2025). Absence of any measurable level of sperm,whereby spermatozoa cannot be observed even after centrifugation of the semen pellet. "Moreover, the prostaglandin D2 synthase (PTGDS) gene, which codes for an enzyme, was found to be significantly lower in patients with obstructive azoospermia compared to those with non-obstructive azoospermia (NOA), underlining its potential as a diagnostic biomarker for obstructive azoospermia." (PMID 40001966, 2025).
breast carcinoma (5 papers, 2020 to 2025). "Using PROGgeneV2 webtool, we found the high expression of cMYC, KLF4, and PTGES2 are associated with poor survival whereas the high expression of PTGDS is associated with better survival in patients with breast cancer." (PMID 33494773, 2021). "The expression of PTGDS was significantly higher in stromal TILs than in ductal epithelial cells in breast cancer specimens, consistent with the results of bioinformatics analysis." (PMID 32047563, 2020). "We further screened the differentially expressed genes between immunotype A and B and identified a novel breast cancer immune-related gene, prostaglandin D2 synthase (PTGDS) and higher PTGDS mRNA expression level was positively correlated with earlier TNM stage." (PMID 32047563, 2020). "Therefore, we analysed the possible role of PTGDS in breast cancer through bioinformatics analysis and histological evaluation." (PMID 32047563, 2020). "There existed rare studies on the biological function of PTGDS in breast cancer." (PMID 32047563, 2020). "The expression level of PTGDS in breast cancer tissues was identified by IHC." (PMID 32047563, 2020). "PTGDS was expressed heterogeneously in breast cancer tissues and both nuclear and cytoplasmic localization of PTGDS could be observed." (PMID 32047563, 2020). "PTGDS suppresses tumor growth via Wnt/β‐catenin modulation, while AIF1L plays a key role in regulating the cytoskeleton in breast cancer, contributing to cellular structure and function." (PMID 40784724, 2025).
colitis (5 papers, 2015 to 2025). Inflammation of the colon. "The expression of MMP-9, PTGDS, SLC26A8, and CD160 in colitis was increased in the IBD mouse model, whereas the expression of TLR5 was downregulated." (PMID 36733384, 2022). "WB and immunofluorescence experiments confirmed that the expression levels of MMP-9, PTGDS, SLC26A8, and CD160 in colitis were significantly increased, whereas that of TLR5 were decreased." (PMID 36733384, 2022). "Screening of disease markers for colitis in mice using a machine-learning approach revealed that the expression levels of SLC26A8, MMP9, PTGDS, and CD160 were significantly elevated in colitis tissues, whereas the expression level of TLR5 was significantly reduced." (PMID 40110435, 2025).
melanoma (5 papers, 2022 to 2025). A malignant, usually aggressive tumor composed of atypical, neoplastic melanocytes. "Moreover, in-vivo study found that PTGDS deficiency promoted the growth of melanoma through accelerating vascular hyperpermeability, angiogenesis, and endothelial-to-mesenchymal transition, which could be reversed by PGD2 receptor agonist." (PMID 39706989, 2025). "Previous investigations reported that PTGDS was highly expressed in high‐grade serous ovarian carcinoma, the endothelial cells of melanoma and oral squamous cell carcinoma." (PMID 39706989, 2025). "According to recent studies, PTGDS was found to be overexpressed in hepatocellular adenoma, ovarian carcinoma, and malignant melanomas." (PMID 39641239, 2024).
diffuse large B-cell lymphoma (4 papers, 2022 to 2025). "PTGDS has been observed to be upregulated in patients, such as those with diffuse large B-cell lymphoma, and is correlated with unfavorable outcomes." (PMID 39355132, 2024). "Here, we aimed to explore the expression and function of PTGDS in diffuse large B-cell lymphoma (DLBCL), especially the potential role of PTGDS inhibitor, AT56, in lymphoma therapy." (PMID 34743203, 2022).
glioma (4 papers, 2007 to 2022). A benign or malignant brain and spinal cord tumor that arises from glial cells (astrocytes, oligodendrocytes, ependymal cells). "The expression levels of proteins such as VTN, APOA1 and PTGDS were found to be highly up regulated in GBM as compared to low grade gliomas." (PMID 34055594, 2021). "While cumulative fold change of three peptides of VTN, PTGDS and C3 in GBM were found to be upregulated in GBM as compared to low grade glioma." (PMID 34055594, 2021).
Insulin resistance (4 papers, 2019 to 2024). Increased resistance towards insulin, that is, diminished effectiveness of insulin in reducing blood glucose levels. "High PGD2 levels have been shown to enhance insulin sensitivity, and KD of PTGDS results in an opposite effect resulting in insulin resistance, but also nephropathy and atherosclerosis." (PMID 35948367, 2022).
Allergy (3 papers, 2015 to 2024). An allergy is an immune response or reaction to substances that are usually not harmful. "PTGDS catalyzes the conversion of prostaglandin H2 to prostaglandin D2, which is known to have several pharmacological functions such as the development of allergy, asthma, and inflammation." (PMID 38167633, 2024).
coronary artery disease (3 papers, 2012 to 2025). "Serum PTGDS levels are positively associated with the severity of coronary artery disease, suggesting its potential as a biomarker for atherosclerotic coronary artery disease." (PMID 40414290, 2025).
dementia (3 papers, 2006 to 2023). Loss of intellectual abilities interfering with an individual's social and occupational functions. "The expression level of PTGDS is related to dementia, with its expression being regulated both directly and indirectly by estradiol." (PMID 37799732, 2023).
endometrial cancer (3 papers, 2021 to 2024). Primary or metastatic malignant neoplasm involving the endometrium (mucous membrane that lines the endometrial cavity). "Additional co-expression analysis studies have shown that AKT1, TICRR, PPIF, ANO1, and PTGDS are possible regulators of endometrial cancer tumorigenesis." (PMID 39596419, 2024). "Interestingly, the expression of ZNF558 and PTGDS was significantly decreased in endometrial cancer in this analysis." (PMID 35163161, 2022). "Almost 20,000 genes were correlated with PTGDS expression in endometrial cancer, and according to GSEA and GO term analysis, they were mainly associated with immunological processes, including regulation of the inflammatory response, leukocyte activation, or adaptive immune response." (PMID 35163161, 2022). "Moreover, it has also been reported that LGR5, SST, ZNF558, and PTGDS may be involved in the development and progression of endometrial cancer." (PMID 35163161, 2022). "For instance, researchers found that Prostaglandin D2 Synthase (PTGDS) predicted poor survival, while ANO1 might be a potential marker for good prognosis in endometrial cancer by WGCNA." (PMID 33936173, 2021).
endometritis (3 papers, 2016 to 2024). An acute or chronic, usually bacterial infectious process affecting the endometrium. "Both subclinical (SE4) and clinical (CE4) endometritis groups displayed increased PTGDS expression at 4 weeks postpartum, with fold changes of 1.36 ± 0.34 and 1.81 ± 0.32 (p = 0.070), respectively." (PMID 39273135, 2024). "While its expression showed some inconsistency, there was a notable increase in PTGDS expression in cows with clinical endometritis at 4 weeks postpartum." (PMID 39273135, 2024). "CNR2 showed a time-dependent pattern in endometritis, and PTGDS expression was elevated in clinical endometritis at 4 weeks postpartum." (PMID 39273135, 2024). "PTGDS expression also showed an interesting pattern in relation to endometritis." (PMID 39273135, 2024). "Here, we examined the anti-inflammatory roles of the lipocalin-type prostaglandin D2 synthase (L-PGDS)/PGD2 and DP1 receptor regulatory pathways in bovine endometritis." (PMID 36435808, 2022).